CD24 (CD24 molecule)
Diseases named in the same sentence as CD24 in open-access papers (continued):
Sharing a sentence is not in itself a finding about the gene and the disease.
tumor (continued). "Therefore, we performed a detailed expression analysis of the most frequently discussed putative markers of CSCs in PDAC (i.e., CD24, CD44, EpCAM, CD133, and nestin) in both human primary tumor samples and in the respective cell lines derived from those tumors." (PMID 27414409, 2016). "Similar results have been reported in carcinogen-induced urothelial tumors, where initiation of tumors in CD24-/- mice was significantly delayed, but tumor incidence was not significantly different between wild-type and CD24-/- mice 28 weeks after treatment with carcinogen." (PMID 26978528, 2016). "Only 50 cells of triple positive CD44+/ESA+/CD24+ cells could form a tumor whereas 1 × 104 CD44−/ESA−/CD24− cells could not." (PMID 25849939, 2015). "The function of Bregs from tumor tissues was not examined because the MFI of CD24 was decreased in IL-10+ B cells, less than in IL-10− B cells from tumor (P < 0.05) and few CD24hiCD38hiBregs were detected in tumor tissues, as confirmed by newly published research." (PMID 26378021, 2015). "To further investigate the absence of differences in tumor initiating potential (as determined by time to palpability) among the cells sorted for CD44/CD24, we analyzed whether any sub-population was enriched for ALDH." (PMID 26449187, 2015). "Interestingly, we found that tumours from CD24- cells did not express the CD24 protein, and neither did they express the stemness markers CD47, EpCAM and Oct3/4." (PMID 25932953, 2015). "Only 5000 cells of CD44+/CD24-/ cells could form a tumor whereas 1 × 104 CD44-/CD24- or ESA-/CD24+ cells could not, suggesting that CD44+/CD24-and ESA+/CD24- cells have characteristics of cancer stem-like cells." (PMID 26338199, 2015). "Moreover, two other recent studies on a panel of tumor markers demonstrated that CD24 expression was not an independent prognostic factor for patients with GC." (PMID 25503963, 2014). "Of all the tested markers, CD24, SSEA-4, SSEA-1 (CD15) CXCR4, E-cadherin and CD44v6 were expressed on the EpCAM positive population of the tumorigenic luminal-like xenograft cells, and thus candidates for defining functionally different luminal tumor cell subpopulations." (PMID 25419568, 2014). "Instead, drug-induction suggested decrease for ITGB1/CD29c and ALDH1B1, while CD24, CD44, CD166, ALDH1A1 and Lgr5 were unchanged as detected by signals from microarrays with pooled tumor RNA from indomethacin-treated patients versus pooled tumor RNA from control patients." (PMID 25340937, 2014). "ALDH1 enzyme activity defines a subpopulation of tumor cells which exhibit stem cell-like properties and whose prevalence correlates with survival in PC Additionally, a number of cell surface markers are co-expressed with ALDH1, such as CD44, CD24, CD133, and CXCR4." (PMID 24652403, 2014). "Notably, DT-22 tumours generated in vivo from the CD24 negative population were found to contain rare CD44+CD24low+ cells (<4%)." (PMID 23982961, 2013). "However, FACS analysis of the serially transplanted tumours showed that the relative size of the individual CD24/CD29 subpopulations did not significantly changed." (PMID 24069241, 2013). "CD24 being an epithelial marker, it may not be expressed in all cancers but seems to have a significant role in those expressing tumours." (PMID 22693526, 2012). "The difference in the relative frequency of CD44+/CD24- and ALDH1+ cells between basal-like and HER2+ tumor subtypes may reflect their distinct cell-of-origin or the alteration of stem cell-like gene expression programs due to tumor subtype-specific transforming events." (PMID 22452810, 2012). "Given the striking association between the ability of fibroblasts to secrete PGE2 in vitro and the ability to expand CD44+/CD24−/EpCAM+ cells and support tumor growth, we speculated that perhaps PGE2 signaling enhances the tumor promoting phenotypes of fibroblasts." (PMID 21957456, 2011). "ALDH1 status did not correlate with presence of CD44+/CD24- tumor cells." (PMID 21957977, 2011).
tumor (continued). "In addition, NDRG2 may act as a tumor suppressor by regulating different molecules, such as TGF-β1 and CD24, which might lead to greater inhibition of HCC." (PMID 21676268, 2011). "Since CD44 and CD24 expression alone could not be used to classify cell lines based on tumor subtype, we examined whether together these markers might be able to categorize cell lines." (PMID 20964822, 2010). "Since CD44 and CD24 were not useful markers to classify tumor cells, we wanted to determine whether additional lineage markers might be able to refine cellular differentiation states." (PMID 20964822, 2010). "We favor the speculation that the CD24 signals the presence of DAMP in a tumor micro environment, thereby augmenting inflammatory response to facilitate pathological tumor progression in GDF3-CD24 pathway-positive B16 F1/F10 but not -negative G-1/G-5 cells." (PMID 20950440, 2010). "Collectively, these data indicated that the specific interactions of SDF-1 with their receptor CXCR4 that expressed on mammosphere cells are likely to occur in tumor-stromal niches, and these interactions may be responsible for the proliferation of CD44+CD24- cells." (PMID 20569497, 2010). "This includes blocking “do not eat me” signals like CD47-SIRPα or CD24-Siglec-10 to enhance phagocytosis by macrophages, inhibiting monocyte recruitment or differentiation via pathways like CSF-1/CSF-1R, or attempting to repolarize M2-like TAMs towards an anti-tumor M1-like state." (PMID 40458806, 2025). "Notably, in preclinical research related to OC, suppressing the expression of CD47 and CD24 or blocking them with anti-CD47 and anti-CD24 mAbs was found to enhance macrophage-mediated phagocytosis, thus resulting in a significant reduction in the growth of xenograft tumours." (PMID 38702326, 2024). "Hence, tumours from some patients are at least partially negative for surface CD24." (PMID 38702326, 2024). "Furthermore, when macrophages were depleted, CD24 knockout animals but not wild-type mice displayed a significant reduction of the decrease in tumor load, suggesting that the antitumor effect may be brought on by macrophage-mediated phagocytosis." (PMID 38279998, 2024). "Despite this, these tumors were not eliminated any faster, indicating that the host induced CD24 upregulation in WT or control tumors was suitable to maximize viral cytotoxicity, whereas the addition of exogenous expression offered a further proliferative advantage exploited by the tumor." (PMID 38214542, 2024). "Starting with the EpCAM, Vimentin and CD24 immunofluorescence grey levels for each nucleated cell, we used a supervised machine learning approach to predict whether an imaging field comes from a metastatic or non-metastatic tumour." (PMID 37975646, 2023). "Delaying CD24-Fc administration at the time of the booster would theoretically have the desired effect of suppressing DAMPs, limiting non-specific tissue damage and suppressing inflammation through blockade of NF-κB activation without suppressing the anti-tumor effect." (PMID 37346042, 2023). "However, the data showed that CD24 coupled to DOX ameliorated the toxicity of DOX and, surprisingly, did not alter the binding affinity of the G7 antibody to the antigen and was able to target and inhibit Huh-7 tumour growth in vivo effectively and prolong and increase survival in mice." (PMID 38137380, 2023). "Moreover, macrophage depletion considerably inhibited the reduced tumor burden in CD24-knockout mice but not in wild-type mice, indicating that the anti-tumor effect may be attributed to macrophage-mediated phagocytosis." (PMID 35978372, 2022). "Furthermore, IL-15 production by CD24+CD29+EpCAM+ epithelial cells was higher in PyMT tumors than in normal tissue and the deletion of tumor-expressed IL-15 resulted in a decrease of ILC1s, a downregulation of granzyme B and C expression, and a reduced tumor control." (PMID 36115839, 2022).
tumor (continued). "Furthermore, we found that as few as ten ALDH+CD44+CXCR4+CD24+-PCa cells, but not other subsets, could develop a palpable tumour within 100 days of implantation." (PMID 34247196, 2021). "We anticipate that a bimodal approach using a CD24-targeted FIGS contrast agent with antibody–drug conjugates, immune blockade, or immunostimulatory CARs may link precision surgical therapy with the postsurgical irradiation of unresected tumor deposits, ultimately benefiting cancer patients." (PMID 33260974, 2020). "However, its role remains complex since both tumor-derived CD24-positive and CD24-negative cells may be chemoresistant with stemness properties, depending on the cancer type." (PMID 30551640, 2018). "However, ANV cells were not able to generate CD44+CD24+ primary MMC tumor cells, in vitro." (PMID 24324806, 2013). "Interestingly, although ER expression was observed in 50 of the 121 (41.3%) patients with CD44/CD24 data, the presence of CD44+/CD24- tumor cells was not significantly correlated with positive ER expression in all patients and in patients with recurrence or metastasis." (PMID 22762532, 2012). "Anti‐CD24 SWA11 mAb has been developed to be conjugated with exotoxin, which significantly induced death of tumor cells without toxicity to normal tissues." (PMID 41346572, 2025). "Due to the absence of anti-CD24 mAb and ALP triggered self-assembly property, Cy5.5SAMIs exhibited limited accumulation of fluorescence signal in the tumor regions." (PMID 38971872, 2024). "While CD24 does not directly interact with NKG2D, its expression on cancer cells can influence the tumor microenvironment and the expression of NKG2D ligands on tumor cells, thereby affecting the efficacy of NKG2D-mediated immune surveillance." (PMID 38881902, 2024). "Conversely, CD24, CD31, and CD40, though not overexpressed in tumor samples, showed a significant correlation with nodal involvement in LCa patients (p < 0.01)." (PMID 38902710, 2024). "We gene-modified human T cells but found that the overexpression of CD24 did not circumvent CV1-mediated depletion of T cells and in fact compromised tumor control." (PMID 38828721, 2024). "For specific tumor types that do not seem to produce EpCAM + CD45- cells, the classification based on high CD44 and low CD24 expression (CD44 + /CD24 − /low) has been introduced." (PMID 38331871, 2024). "A significant correlation between tumor markers ALDH1-A1, -A2, and -A3, CD24, CD44 on one hand, and CD276, on the other hand, was not computed." (PMID 35563359, 2022). "The CD44/CD24 ratio expressed on INJ, PUMP (ASA), and PUMP (OP) treated tumor tissues was not significantly different from GEM-treated tumor tissue." (PMID 35892853, 2022). "The expression of stem cell markers was also evaluated on primary tumor cells from 55 PDAC patients who underwent pancreatectomy with radical intent, revealing that CXCR4+/CD133+ and CD24+ cells, but not ESA+CD24+CD44+, are independent predictors of mortality." (PMID 36142575, 2022). "The protein expression of MMP1, CD24, SDC1, and SPP1 was significantly correlated with tumor grade and subtype but not with tumor stage." (PMID 35037689, 2022). "The CD138+CD3+ tumor cells also expressed high levels of IGHM, CD27, and XBP1, but were absent of CD19, CD22, CD24, and CD10 expression." (PMID 36494694, 2022). "We designed an antibody cocktail of lineage markers (CD24, CD31, CD45.2, CD49f, EpCAM, TER-119 and LYVE-1) to exclude non-fibroblast cells from the single cell suspension of tumours analysed by flow cytometry (FCM)." (PMID 34016130, 2021). "Orthotopic tumour models were developed from CD44+, CD44+ α2β1+, ALDH+ CD44+ α2β1+ and ALDH+ CD44+ CXCR4+ CD24+ cells with or without HOXB9 knockdown." (PMID 34247196, 2021). "It has been reported that CD44−/CD24+ and ALDH1+ tumor cells represent two distinct tumor cell populations not only localized in different regions of the primary tumor tissue but also expressing distinct EMT and MET gene profiles." (PMID 32667137, 2020).
tumor (continued). "Within EDW01, but not ED03, there were regions of tumour cells that appeared to lack both CD24 and CD44; however, these regions in EDW01 that are negative for CD44/CD24 do not increase over passage number." (PMID 33276802, 2020). "Compared with before NAC, the expressions of CD44, N-cadherin, β-catenin, and Vimentin in tumor tissues were significantly downregulated after NAC, while the expressions of E-cadherin and CD24 had no statistically significant change after NAC." (PMID 33282946, 2020). "It is worthy pointing out that both parental cells and tumor sphere cells were not homogenous because the labeling intensity differed markedly, such as the CD44 and CD24 fluorescent intensity." (PMID 31196164, 2019). "Although we digested the MDA-MB-231 tumor spheres into single cells and injected these into the zebrafish, these did not migrate until the sixth day, suggesting that CD44+CD24- is not a suitable marker for MDA-MB-231 stem cells." (PMID 31612865, 2019). "Whilst the ER status of BCSCs enriched in ER + ve tumor cells resistant to endocrine therapy is not clear, evidence suggests the ER-ve status of both CD44+CD24−/low and ALDH1+ BCSCs." (PMID 31336602, 2019). "In particular, a subset of β-catenin-positive cells from HNSCC, expressing the tumor stem cell marker CD44, were also shown to co-express CD24 and CD29 and to promote non-adherent tumor sphere growth and seed tumors at low numbers in mice." (PMID 30029671, 2018). "Following long-term HER2 siRNA treatment, the population distribution remains largely the same, without any detectable emergence of a CD24-/CD44+ population, suggesting no enrichment of tumor initiating cells." (PMID 29879129, 2018). "We found that silencing of TLR2, but not RAGE, TLR4, or CD24, inhibited the migratory ability of the living cancer cells, indicating that HMGB1 regulates tumor cell invasion through TLR2 in vitro." (PMID 29615080, 2018). "CD24 and TIM‐3 are negative receptors that inhibit HMGB1 immune activity in macrophages, DCs and tumour cells." (PMID 28039939, 2017). "Like CD44+CD24+ESA+ cells, 500 CD133+ PC cells generated visible tumors that histologically indistinguishable from the primary tumor." (PMID 28245823, 2017). "Thus our finding that lack of CD24 does not impair tumor incidence in the MMTV-PyMT and Apc1572T/+ models (as assessed by the age at which tumors first become palpable) could suggest that CD24 may not have a functional role in determining the properties of CSCs in these models." (PMID 26978528, 2016). "Therefore, non-CD24+CD90+ tumor cells could not be investigated in the subsequent experiments." (PMID 27542270, 2016). "The isolated CD24+ cells exhibit typical CSC characteristics, and initiate tumor growth in non-obese diabetic/severe combined immunodeficiency (NOD/SCID) mice at a low cell number." (PMID 24955581, 2014). "The sorted CD44+CD24− CSC, CD44+CD24+, and unsorted tumor cells, but not CD44− cells, formed typical mammospheres in the presence of leukemia inhibitory factor in vitro." (PMID 25301732, 2014). "Here we show that cells with low level surface CD24 expression (CD24low+) and CD24 negative (CD24neg) cells comprise distinct phenotypes in the T-ISC-enriched CD44+CD24neg/low population of TNBC lines and primary dissociated tumour cultures." (PMID 23982961, 2013). "A trend toward higher levels of expression of ALCAM, CD24, and CD44, but not PROM1, was observed in CXs derived from D61540 when compared with their parental tumor." (PMID 24278200, 2013). "Retention of CD44+CD24- phenotype during in vitro and in vivo passages suggest that CD44+CD24-Sca1+ cells may be a highly tumorigeneic phenotype within the primary tumor cells which have characteristics similar to stem-like cells, but they may not be tumor initiating cells." (PMID 24324806, 2013).
tumor (continued). "Eight weeks post-injection, 103 CSC cells successfully formed a tumor (2/4), while non-CD44+/CD24- tumor cells failed to form tumors until attaining 106 cells (1/4) (P<0.05, Fisher’s extract test, Fig. 1B1 and B2)." (PMID 23056395, 2012). "Despite the requirement for IL-6 in mediating the tumor promoting abilities of fibroblasts, we found that IL-6 alone was not sufficient for expansion of CD44+/CD24−/EpCAM+ cells in the MCF7 cell line." (PMID 21957456, 2011). "Of CD44+CD24-/low positive tumours, 33% were grade 1 whereas only 23% of CD44+CD24-/low negative tumours were grade 1 (P = 0.006)." (PMID 22112299, 2011). "Significantly, injection of 1000 CD44+CD24− cells resulted in tumours in 100% (5/5) of mice, whereas 1000 CD44+CD24−-depleted cells failed to form tumours in any mice (0/5)." (PMID 18268494, 2008). "The expression of CD24 and TPPP3 in the controls is not surprising, and the expression of other tumour biomarkers in control 3 could be due to a previous mechanical obstruction of the fallopian tube." (PMID 41160707, 2025). "However, in HCC, CEACAM6 expression was not prominent, while CD24 expression was significantly higher compared to normal liver tissues, spatial transcriptomics (HRA000437) of patient tumor specimens corroborated the findings." (PMID 40860182, 2025). "Also, in both our cell line and tumour analysis, some samples contained CD271+ without CD24+CD271+ cells, but CD24+ and CD24+CD271+ cells always co-existed; this is also true in these scRNAseq cases." (PMID 40754577, 2025). "CD24 alters Signal Transducer And Activator Of Transcription 3 (STAT3) expression via SRC Proto-Oncogene, Non-Receptor Tyrosine Kinase (Src), which leads to tumor invasion and metastasis." (PMID 38360723, 2024). "The results showed that not every tumor tissue expressed CD44, CD24 or ABCG2, but the expression of EpCAM could be detected." (PMID 36132125, 2022). "For example, one study identified two tumour initiating cell subsets within the BCSC population and demonstrated active Notch1 signalling in the more proliferative, invasive and metastatic subpopulation (CD44+/CD24low) but not the other (CD44+/CD24–)." (PMID 34295896, 2021). "In addition, CAFs promote tumor forming ability and stemness when co-implanted with PCa cells in mice xenografts, and importantly, these tumor-repopulating cells were found to be CD44-positive and CD24-negative." (PMID 32754615, 2020). "Although pancreatic CSCs were described nearly ten years ago as CD44+/ CD24+/EpCAM+ cells or CD133+ cells, no study has determined the co-expression of all of these markers in PDAC either directly in the tumor samples or in the human PDAC cell lines derived from primary tumors." (PMID 27414409, 2016). "CD24 and CD133 co-expression based on tumor differentiation was not significantly different." (PMID 27099673, 2016). "Based on the observation that tumor cells in hepatic metastasis expressed CD24 despite absent expression in the primary tumor, we speculate that while tumor cells undergo EMT or develop mesenchymal features, CD24 expression is downregulated." (PMID 27203385, 2016). "Quantitative imaging phenotypes may be a surrogate marker for the tumor’s molecular makeup and allow for the identification of tumors that express VEGF, EGFR, or CD24, regardless of qualitative imaging features." (PMID 26207380, 2015). "In contrast, in tumor samples lacking ER expression or with low ER transcriptional activity (as reflected by low PR expression, PRlow), hypoxia promoted the expansion of CD44+CD24−/low cells." (PMID 26372732, 2015). "We found that CD24 could increase the expression of phospho-Lyn (Y396), but not phospho-Src, phospho-Fyn or phospho-lck in CRC cells, which indicated a tumor-type dependent induction." (PMID 22731636, 2012).